INS (insulin)
Diseases named in the same sentence as INS in open-access papers (continued):
Sharing a sentence is not in itself a finding about the gene and the disease.
Insulin resistance (continued). "Given that the frequency of taking biguanides or insulin therapy was slightly higher in the non‐sarcopenia group, further studies with detailed assessment of insulin resistance, such as the use of an oral glucose tolerance test, might help clarify this issue." (PMID 31074209, 2019). "In the evaluation of the HOMA model using baseline glucose and C-peptide concentrations, T allele carriers presented greater insulin sensitivity (%S) (p = 0.021) and lower insulin resistance (p = 0.020) than noncarriers of this allele." (PMID 30700996, 2019). "The results showed the phosphorylation of tyrosine 632 of IRS-1 after treatment of cells with palmitate (to make the diabetic model of insulin resistance) and stimulation with insulin (to initiate the signal pathway) in TNF-α-downregulated cells was 45% (p < 0.05) higher than the normal cells." (PMID 30863203, 2019). "Though there might be intrahepatic insulin resistance in these mice, the whole-body insulin sensitivity was presumably increased due to the therapeutic effect of the PPARγ agonist." (PMID 30871156, 2019). "Insulin resistance in these rats was determined by measuring serum insulin and HOMA-IR." (PMID 31340583, 2019). "Through GO enrichment analysis and pathway analysis for genes, we found that “regulation of metabolic process,” “insulin secretion,” “lipid metabolic process,” and “very long-chain fatty acid-CoA ligase activity” were significant and highly related to insulin resistance." (PMID 31507635, 2019). "These solid results indicate that HZ has a promising bioactivity in regulating obesity and insulin sensitivity, which may have potential for clinical application in preventing from hepatic steatosis and insulin resistance." (PMID 31836013, 2019). "Here we sought to overcome these common pitfalls by using homogeneous, genetically defined mutant hypomorphic conditions of the insulin signaling pathway to model diabetes type II (insulin resistance) together with a control strain, where all stocks have the same genetically homogenized background." (PMID 30805360, 2019). "Furthermore, DYRK1A overexpression ameliorated chronic high insulin-induced insulin resistance in SH-SY5Y cells as well as in primary rat neurons." (PMID 31723029, 2019). "Wdr76−/− mice had improved glucose tolerance and insulin sensitivity, suggesting that WDR76 deficiency could reduce HFD-induced insulin resistance." (PMID 31873167, 2019). "Reduced phosphorylation of both PI3K and AKT could explain impaired insulin signaling and development of insulin resistance, as previously demonstrated." (PMID 31048842, 2019). "Thus, disrupted insulin signaling—the most common of which is insulin resistance—can give rise to dysfunctions in both peripheral organs and the central nervous system (CNS)." (PMID 29973864, 2018). "Thus, restoring adiponectin levels is beneficial for attenuating insulin resistance and improving insulin sensitivity." (PMID 29601521, 2018). "Our data demonstrated that Mfn‐2 overexpression could markedly decrease the lipotoxicity of NEFAs on mitochondrial function and insulin sensitivity, indicating that Mfn‐2 is a potential therapeutic target for insulin resistance in NASH." (PMID 29602237, 2018). "This condition of insulin resistance could explain the results found in glucose-stimulated insulin secretion by the islets of animals." (PMID 29614007, 2018). "A person living with T2DM does not produce enough insulin (insulin deficiency), or has body cells that are not able to use insulin properly (insulin resistance)." (PMID 29304014, 2018). "Impaired insulin signaling through IRS1 to Akt is often observed in insulin resistance and has been hypothesized to be upstream of defects in GLUT4 translocation." (PMID 29599292, 2018). "In the present study, whether theaflavins could promote liver mitochondrial biogenesis and alleviate insulin resistance was examined using an insulin-resistant HepG2 cell model." (PMID 30572687, 2018).
Insulin resistance (continued). "Since the recruitment of macrophages into adipose tissue indicates chronic inflammation accompanied with obesity and insulin resistance, decreases in macrophage infiltration further supports the lean phenotype and preserved insulin sensitivity in p533KR/3KR/mdmx-/- mice." (PMID 29484110, 2018). "Neither of the monocyte subsets demonstrated correlation with insulin resistance; however, fetuin-A showed a negative association with insulin sensitivity." (PMID 29582352, 2018). "Compared with the lean control mice, diabetic ob/ob mice exhibited remarkable insulin resistance, as manifested by significant higher fasting serum insulin level and homeostasis model assessment-estimated IR (HOMA-IR) index, and deteriorated oral glucose tolerance." (PMID 30140027, 2018). "This also confirms previous findings showing a negative correlation of C18:3 and its precursor with insulin resistance and positive association with insulin sensitivity." (PMID 29940972, 2018). "The observed association for increased pancreatic beta cell function and reduced insulin sensitivity may reflect an initial compensation by beta cells for the obesity-induced insulin resistance, by increasing insulin secretion." (PMID 30225524, 2018). "For pregnant women with GDM, we found negative correlations between probiotics supplementation and fasting serum insulin (OR -2.94, 95%CI [-5.69, -0.20], p = 0.04) and homoeostasis model assessment for insulin resistance (HOMA-IR) (OR -0.65, 95%CI [-1.18, -0.11], p = 0.02)." (PMID 29782556, 2018). "It is of particular interest that these metabolites may profile mechanisms leading to insulin resistance and vascular disease, given that low dose insulin therapy was added to the Milwaukee protocol, version 4, with statistical improvements in survival." (PMID 30557317, 2018). "However, the presence of “free” insulin in the blood enhances the development of insulin resistance." (PMID 30293998, 2018). "The development of hyperinsulinemia and insulin resistance in murine cardiac hypertrophy is due to the pressure overload boosts in myocardial insulin signaling to Akt (in excess) which adds to the left ventricular reconstruction at an accelerated level and ultimately, a shift to heart failure." (PMID 30344301, 2018). "Adipose depots retain a high degree of insulin responsiveness and insulin resistance ex vivo." (PMID 29402381, 2018). "Disrupted mitochondrial function is thought to at least contribute to muscle insulin resistance, likely due to increased oxidative stress and altered insulin signaling, both of which may be affected by changes in mitochondrial morphology." (PMID 30071599, 2018). "Carriers of the major allele T had lower insulin levels, as estimated by ΔI30/ΔG30 (p = 0.008) and ΔI120/ΔG120 values (p = 0.017), than noncarriers, even after adjusting for insulin resistance (p′ = 0.004 and p′ = 0.006, resp)." (PMID 29675042, 2018). "Also, relative to NW individuals, obese individuals generally show insulin resistance, higher insulin levels, and slower postprandial glucose clearance." (PMID 29498693, 2018). "Therefore, when using the HOMA index to determine insulin resistance, the Indian and Caucasian subjects were shown to be significantly more insulin resistant than the African subjects." (PMID 29351564, 2018). "Th1 cells and IFN-γ, the major Th1 and CTL cytokine, can directly interrupt insulin signaling, leading to insulin resistance in adipocytes and skeletal muscle myocytes, which may contribute to systemic insulin resistance in obesity." (PMID 30459770, 2018). "Statins may directly decrease the synthesis of insulin or reduce insulin secretion, exacerbating insulin resistance, and/or modify insulin signaling in peripheral target tissues." (PMID 29630642, 2018). "Adult subjects with GHD have elevated insulin levels at baseline, and increased insulin resistance." (PMID 29971224, 2018).
Insulin resistance (continued). "Although the role of CA activity and other transporters that might modulate pHi in insulin sensitivity remains largely unexplained, these data altogether pave for pharmacological manipulations of pHi to treat insulin resistance." (PMID 30598026, 2018). "Insulin signal transduction defects will lead to insulin resistance." (PMID 29682407, 2018). "It is therefore feasible that induction of insulin resistance may result in the inability of insulin to promote testosterone synthesis in Leydig cells, and further contribute to hypogonadism." (PMID 29566712, 2018). "Because of liver’s essential role in regulating lipid and glucose metabolism and a potential link between hepatic insulin resistance and hepatic steatosis, we hypothesized that miR199a-5p plays a key role in hepatic insulin sensitivity." (PMID 29540751, 2018). "It was also demonstrated that increased β‐oxidation improved insulin resistance by reducing the triglyceride accumulation and the expression of inflammatory cytokines, two factors that have been shown to reduce the sensitivity to insulin." (PMID 29976786, 2018). "The results of the current study revealed that cardiacApelin and Apj expression were increased in the HF/HCfed rats and these changes were significantly correlatedwith increased serum levels of Apelin and insulin, bodyweight, insulin resistance, inflammatory markers and theatherogenic lipid profile." (PMID 29845798, 2018). "Therefore, as much as insulin resistance can impair glucose availability to insulin dependent cells, the ketone can be utilised as an energy substrate despite the insulin dysfunction." (PMID 29805804, 2018). "In hyperinsulinaemia or insulin resistance states, there may be reduced insulin-mediated suppression of hormone-sensitive lipase, an enzyme responsible for triglyceride mobilization." (PMID 29518910, 2018). "Unfortunately, there is currently no widely-accepted treatment or prevention strategy for GDM, except lifestyle intervention (diet and exercise) and occasionally insulin therapy—which is only of limited effectiveness due to the insulin resistance that is often present." (PMID 30373146, 2018). "However, in initial stages of clinical or experimental prediabetes type 2, e.g. in obesity, the endocrine pancreas compensates for insulin resistance by increasing β-cell mass and insulin secretion." (PMID 30016962, 2018). "In addition, nonesterified fatty acid (NEFA) is an important factor in in the modulation of insulin metabolism, and it has been shown to be positively correlated with insulin resistance." (PMID 30356972, 2018). "Moreover, insulin resistance is a well‐established phenomenon in septic patients and insulin is a potent inhibitor of lipolysis." (PMID 29976786, 2018). "Insulin resistance is a condition in which cells fail to respond to the normal actions of insulin." (PMID 29686650, 2018). "EA can improve the insulin sensitivity of insulin resistance rats; the positive regulation of the AMPK/ACC pathway in the skeletal muscle may be a possible mechanism of EA in the treatment of IR." (PMID 30524482, 2018). "Pregnancy is normally accompanied by progressive insulin resistance due to a combination of increased maternal adiposity and the insulin-desensitizing effects of diabetogenic placental hormones, such as the human growth hormone, corticotropin-releasing hormones, placental lactogen, and progesterone." (PMID 30486265, 2018). "In addition, the homeostatic model assessment (HOMA) for evaluating insulin resistance was calculated from fasting glucose and insulin concentrations." (PMID 29678421, 2018).
Insulin resistance (continued). "Several studies demonstrated that multiple alterations of miRNAs expression or function are relevant for the development of insulin resistance in type 2 diabetes (T2D); such alterations have been highlighted in multiple insulin target organs including liver, muscles, and adipose tissue." (PMID 30469501, 2018). "Finally, to prove the role of miR-214 on endothelial MGO-mediated insulin-resistance, we analyzed the effect of miR-214 inhibitor and miR-214 mimic on insulin-dependent phosphorylation of Akt." (PMID 29425121, 2018). "Also, there was an elevation in the levels of glucose, fructosamine (protein glycation), and insulin levels with hepatic insulin resistance (HOMA-IR) and adipose resistance (IDA-IR)." (PMID 30026756, 2018). "We did not have measurements of insulin beyond its baseline assessment, which impedes us in evaluating the evolution of insulin resistance and its association with BCAAs." (PMID 30518023, 2018). "Therefore, increasing the levels and translocation of GLUT4 is a crucial factor in regulating glucose tolerance and insulin sensitivity to prevent the development of insulin resistance." (PMID 29601521, 2018). "We aimed to test the hypothesis that selenoprotein P (SELENOP), a hepatokine involved in the development of both insulin resistance and impaired insulin production in mice, is related to future onset of hyperglycemia in humans." (PMID 30425271, 2018). "One may hypothesize that lack of response of AT SIRT1 to insulin represents an early metabolic abnormality in this group, even before the onset of overt insulin resistance, measured as a decreased insulin-stimulated glucose uptake." (PMID 29417372, 2018). "Therefore, reduced responsiveness of skeletal muscle to insulin, that is, insulin resistance (IR), is a critical aspect of type 2 diabetes mellitus (T2DM) development." (PMID 30249008, 2018). "CPR-IR could be an index of insulin resistance that is minimally affected by hepatic insulin clearance." (PMID 29791512, 2018). "It is hypothesised that animals on a high-fat diet have increased inflammation, which leads to decreased glucose-induced insulin secretion and ultimately insulin resistance." (PMID 30400297, 2018). "Insulin resistance: is a pathology in which cells fail to respond normally to the hormone insulin." (PMID 29986479, 2018). "Thus, it is conceivable that during a state of insulin resistance, glucocorticoids act with insulin to further promote lipogenesis." (PMID 30310815, 2018). "This led to the belief that statins might influence glucose homeostasis by decreasing insulin production or increasing insulin resistance, or both." (PMID 29649995, 2018). "The reduced expression of insulin and IGF-1 receptors might explain the insulin resistance registered in the AD brain, thereby affecting negatively the insulin transduction pathway." (PMID 30096758, 2018). "Insulin resistance is defined as a decrease in tissue response to insulin stimulation thus insulin resistance is characterized by defects in uptake and oxidation of glucose, a decrease in glycogen synthesis, and, to a lesser extent, the ability to suppress lipid oxidation." (PMID 30170598, 2018). "Since insulin resistance is directly correlated with BMI, it may be the case that females with higher BMI are the most insulin-resistant, with important detrimental effects on the brain reserve in dementia." (PMID 30135519, 2018). "Skeletal muscle is the primary tissue for insulin-stimulated glucose uptake, plays a paramount role in the regulation of blood glucose levels, and is therefore recognized as an important therapeutic target tissue for insulin resistance and T2DM." (PMID 29710819, 2018). "An eight-year longitudinal study involving nonelderly people has showed that dyslipidemia and high blood pressure are associated with insulin resistance, and VLDL-cholesterol are correlated with impaired early phase insulin secretion (Kekalainen, Sarlund & Laakso, 2000)." (PMID 29568712, 2018).
Insulin resistance (continued). "The present study evaluated the relative influence of body mass index (BMI) on insulin resistance (IR), first-phase insulin secretion (FPIS), second-phase insulin secretion (SPIS), and glucose effectiveness (GE) at a fixed fasting plasma glucose level in an older ethnic Chinese population." (PMID 29377927, 2018). "Future work including a glucose tolerance test along with fasting insulin and glucose measures will provide insight into whether the rat model of postnatal hyperoxia recapitulates the insulin resistance found in human adults born preterm." (PMID 29651255, 2018). "The ability of zinc to regulate insulin signaling processes suggests that this metal ion might have utility to be targeted experimentally to improve the management and/or treatment of insulin resistance." (PMID 29373583, 2018). "Current research efforts into the etiology and pathogenesis of T2DM, are focused on defining aberrations in cellular physiology that result in development of insulin resistance and strategies for increasing insulin sensitivity, along with downstream effects on T2DM pathogenesis." (PMID 29518003, 2018). "Central insulin resistance could reduce the likelihood of seeing an effect of ICV insulin administration on hippocampal-dependent tasks, given it's non-specific targeting." (PMID 30619085, 2018). "Chronically elevated leptin levels in obesity may result in decreased responsiveness of pancreatic β-cell receptors and lead to increased insulin secretion, contributing to the occurrence of insulin resistance." (PMID 29551973, 2018). "This insulin resistance, in the liver and muscle, characterized by a down-regulation of insulin signaling may unveil the overreaction at the tissue level, and may also be used to predict the effectiveness of treatment." (PMID 29760586, 2018). "Indeed, saturated fatty acids are major contributors to this process, as they directly impair insulin sensitivity in adipocytes and muscle cells in culture through pro-inflammatory effect-induced insulin resistance." (PMID 29333341, 2018). "Although retrograde signalling from the mitochondria to the nucleus is well described it seems unlikely that this mitochondrial oxidant-induced insulin resistance requires changes in transcription because induction of mitochondrial oxidants acutely impairs insulin action." (PMID 29402381, 2018). "The molecular mechanisms underlying insulin resistance, impairment of insulin signaling, and exhaustion of pancreatic β-cells are not completely elucidated." (PMID 30445764, 2018). "Insulin resistance is a multifaceted metabolic condition characterized by the fact that insulin-sensitive tissues are not able to respond adequately to physiological concentrations of insulin." (PMID 29510489, 2018). "On the other hand, OCN could improve insulin resistance by decreasing inflammation and promote insulin signaling as well as the expression of Slc2a4/GLUT4." (PMID 30186852, 2018). "Given that the key defining parameters of the MS are cardiovascular impairments in conjunction with insulin resistance, and since people suffering from the MS often have chronically elevated plasma insulin levels, it is worthwhile to examine the role of insulin in healthy endothelium." (PMID 29209827, 2018). "While mounting evidence supports the conclusion that IH leads to insulin resistance, research on how decreased insulin sensitivity may lead to the development of OSA is scant due in part to the challenging experimental designs." (PMID 30127766, 2018). "Insulin resistance is the excessive insulin accumulation in blood with normal blood glucose levels." (PMID 29541033, 2018). "In addition, acute administration of glucagon has been shown to induce insulin resistance, which would also result in an impaired glucose-lowering effect of insulin." (PMID 29558502, 2018).